BTG1 (BTG anti-proliferation factor 1)
Diseases named in the same sentence as BTG1 in open-access papers (continued):
Sharing a sentence is not in itself a finding about the gene and the disease.
tumor (continued). "B cell translocation gene 1 (BTG1) is another tumor suppressor gene." (PMID 25115181, 2014). "Therefore, down-regulation of BTG1 via miR-454-3p presents a possible strategy to sensitize tumor cells to radiotherapy." (PMID 25115181, 2014). "Down-regulation of BTG1 by miR-454-3p renders tumor cells sensitive to radiation." (PMID 25115181, 2014). "The lack of BTG1 and B2M mutations in tumor tissue DNA suggests that ctDNA fragments with these mutations may have originated from distant metastatic tumor tissues with different genotypes in this FL patient." (PMID 35795062, 2022). "Importantly, several studies have shown that BTG-1 may induce apoptosis in tumor cells, suggesting that BTG-1 may be a tumor-suppressor gene." (PMID 33531999, 2021). "Thus, Btg1 appears to play a role in cerebellar tumorigenesis by regulating the balance between apoptosis and proliferation during MB development, also influencing the number of tumor stem cells." (PMID 32231994, 2020). "How loss of BTG1 function contributes to tumor progression is not well understood." (PMID 26657730, 2016). "It was worth noting that the inhibitory effect of BTG1 on migration and invasion might be positively linked to MMP-9 hypoexpression because MMP-9 degrades various components of the extracellular matrix and enhances the tumor invasive and metastatic potentials." (PMID 26050197, 2015). "Usually, when analyzing the tumor genome by CMA, aberrations larger than 5 MB and additional microdeletions involving the CDKN2A/B, BTG1, EBF1, ETV6, ERG, IKZF1, PAX5, and RB1 genes are taken into account." (PMID 39408811, 2024). "The single-cell transcriptome and single-cell multi-omics analyses revealed that novel tumor-related genes, such as AMIGO2, ZFP36, BTG1, and DLG5, were mainly upregulated in pituitary neuroendocrine tumors." (PMID 38098508, 2023). "We found that the CCL5 ligand secreted by BTG1+RGS1+ Tcm and HSPA1B+ Tcm cells bound to the SDC4/1 receptor on the surfaces of tumor cells." (PMID 37333982, 2023). "As a result, BTG1 and BTG2 are considered as tumor suppressors and closely correlated with tumor cell behavior as well as prognosis." (PMID 38062199, 2023). "StromalScore and ImmunoScore were used to analyze the correlation between APRO (TOB1, TOB2, BTG1, BTG2, BTG3 and BTG4) expression and tumor purity and tumor microenvironment characteristics." (PMID 38062199, 2023). "This research led to the discovery of several new tumor-related genes, including AMIGO2, ZFP36, BTG1, and DLG5." (PMID 38275385, 2023). "The subpopulations with double-positive expression of BTG1 and RGS1 were significantly enriched in tumor lesions." (PMID 37333982, 2023). "On the other hand, similar to antecedent studies, the more frequently altered genes were related to cell cycle regulation (ETV6), tumor suppression (CDKN2A/B), apoptosis regulation (BTG1) and others." (PMID 32607130, 2020). "Also the tumor latency in double-mutant mice, either Ptch1+/−/Btg1+/− or Ptch1+/−/Btg1KO, did not significantly differ from that of control Ptch1+/−/Btg1WT mice (Ptch1+/−/Btg1+/− vs. Ptch1+/−/Btg1WTp = 0.852; Ptch1+/−/Btg1KO vs. Ptch1+/−/Btg1WTp = 0.386; Student's t-test)." (PMID 32231994, 2020). "The tumor volumes of both HCT-15 and HCT-116 cells xenografts were larger than those of BTG1 transfectants by calculation and ultrasonic imaging (p<0.05)." (PMID 27447746, 2017). "BTG (B-cell translocation gene) family includes six proteins (BTG1, BTG2, BTG3, BTG4, Transducer of ErbB-2, and TOB2), which suppresse proliferation, cell cycle progression and induce differentiation as a tumor suppressor." (PMID 27447746, 2017).
tumor (continued). "In contrast, CD8 effector cells exhibited downregulation of multiple key genes involved in tumor-suppressive transcriptional regulation (HIST1H1C, ZNF331, KLF6, and BTG1) and immune activation and trafficking (CXCR4, CD69, and TNFAIP3) in LS carriers, which was more severe in LS-CRC." (PMID 40909768, 2025). "In addition, protein expression analysis of BTG1, CCNG1, EDG1, and TIMP2 in MM tissues in mouse tumor masses treated with LNPs-anti-miR-503 confirmed the q-PCR results and the opposite expression of miR-503 and of its target genes also in vivo." (PMID 39984959, 2025). "This article also defined AMIGO2, ZFP36, BTG1, and DLG5 tumor-related genes." (PMID 39114291, 2024). "We found that CAF subtypes 0 (BTG1+ CAF), 2 (CFD+ CAF), and 4 (IGFBP7+ CAF) were more abundant in the tumor than the normal, while CAF subcluster 1 (OGN+ CAF), 3 (C1R+ CAF), 5 (MFAP5+ CAF), and 6 (SFRP4+ CAF) were more abundant in the normal than the tumor." (PMID 38686196, 2024). "Other genes: BTG1, CD24, KRT19, RAC2 and RGS1 were significantly upregulated in tumour samples." (PMID 39098994, 2024). "Novel tumor-related genes like AMIGO2, ZFP36, BTG1, and DLG5 have been identified." (PMID 38275385, 2023). "Single factor analysis showed that low plasma exosome-derived BTG-1 levels was not related to sex or age (both P > 0.05), but was related to tumor diameter, stage, tumor metastasis, the degree of tumor differentiation, and abnormal CEA levels (all P < 0.05)." (PMID 33531999, 2021). "The results showed that plasma exosome-derived BTG-1 levels were related to tumor diameter, stage, tumor metastasis, the degree of tumor differentiation, and abnormal CEA levels, in accordance with previous findings for BTG-1 protein expression in other cancers." (PMID 33531999, 2021). "Moreover, in Btg1-null MBs, we observed a two-fold increase of cells positive to CD15, which labels tumor stem cells, raising the possibility of activation of quiescent tumor cells, known for their role in long-term resistance to treatment and relapses." (PMID 32231994, 2020). "In MBs developing in Ptch1+/− mice, deletion of Btg1 does not alter tumor and lesion frequencies, nor affect the proliferation of neoplastic precursor cells." (PMID 32231994, 2020). "Moreover, a role for BTG1 and BTG2 as tumor suppressors in both lymphoid malignancies and solid tumors is emerging." (PMID 30350856, 2019). "In addition, there is significant immune infiltration into tumor lesions, and the interaction between BTG1+RGS1+ Tcms and tumor cells via CCL5–SDC4/1 axis may promote tumor progression." (PMID 37333982, 2023). "In addition, the CCL5–SDC4/1 interaction between BTG1+RGS1+ Tcms and tumor cells may promote tumor progression." (PMID 37333982, 2023). "Moreover, in view of the strong increase observed in our Btg1-null MB mouse model of CD15+ tumor stem cells, which can be at the origin of tumor regrowth after years, future investigation may evaluate whether the Btg1 gene is implicated in MB relapse." (PMID 32231994, 2020). "Moreover, scRNA-seq results identified novel tumor suppressor genes (ZFP36, BTG1, DLG5, and ZBTB16), cell apoptosis-inhibitor genes, genes with pro-tumoral functionality (C1Q in TAMs), and many cell cluster-specific genes, including tumor and stromal cell-specific marker genes." (PMID 39114291, 2024). "Interestingly, in MBs, the augmented cell death could make a selection of quiescent CD15+ tumor stem cells, which are increased in MBs lacking the Btg1 gene." (PMID 32231994, 2020).
cancer (36 papers, 2012 to 2026). A tumor composed of atypical neoplastic, often pleomorphic cells that invade other tissues. "In conclusion, aberrant BTG1 mRNA expression was closely linked to carcinogenesis, cancer aggressiveness, and worse prognosis of cancer patients in a tissue-specific manner." (PMID 36339000, 2022). "Btg1 and Btg2 encode highly homologous proteins that are broadly expressed in different cell lineages, and have been implicated in different types of cancer." (PMID 26218146, 2015). "In these ways, APRO family proteins including Tob1, BTG2, and BTG1 have been reported to control/regulate/promote cell proliferation, cell cycle progression, and/or cell differentiation in various types of cancer." (PMID 40918450, 2025). "Progression from LGASC to high-grade carcinoma is associated with additional pathogenic deletions in tumor suppressor genes such as KMT2D and BTG1, and loss of heterozygosity at 18q." (PMID 41301002, 2025). "The goal of this study was to clarify the clinicopathological and prognostic significances of BTG1 mRNA expression and related signal pathways in cancers." (PMID 36339000, 2022). "According to the xiantao database, the BTG1-correlated genes in cancers were analyzed and subjected to the KEGG analysis." (PMID 36339000, 2022). "Stage I + II, II, II + III, III, and III + IV cancer patients with high BTG1 expression showed a short progression-free survival time than those with its low expression (p < 0.05)." (PMID 36339000, 2022). "In UALCAN data, BTG1 expression was lower in N3 than N0, N1 and N2, S2 than S1, and G3 than G1 and G2 cancer (p < 0.05)." (PMID 36339000, 2022). "It is evident that the expression level of BTG1 is regarded as a prognostic biomarker for diverse cancers." (PMID 35774514, 2022). "On the xiantao platform, we discovered the genes that differed between low and high expression groups of BTG1 mRNA in cancers." (PMID 36339000, 2022). "By observing the heat map showing the CNV situation, we found that RUNX1, SCG2, and BTG1 have high heterozygous amplification in various cancers, including ACC, TGCT, and UCS." (PMID 35498539, 2022). "There are contradictory reports on the invasiveness of cancer cells in the exploitation of the BTG1 protein, the other member of the APRO family, as well as those of Tob1 as shown in the introduction." (PMID 36230852, 2022). "According to Kaplan-Meier plotter, a higher BTG1 expression was positively correlated with overall survival rates of all or luminal-B cancer patients (p < 0.05)." (PMID 36339000, 2022). "BTG1 was more expressed in breast normal tissue than in cancer according to xiantao and UALCAN databases (p < 0.05)." (PMID 36339000, 2022). "According to Kaplan-Meier plotter, we found that the higher BTG1 expression was negatively correlated with the overall rate of all, male or G2 cancer patients (p < 0.05)." (PMID 36339000, 2022). "According to the Kaplan–Meier plotter, BTG1 mRNA expression was negatively correlated with the overall survival rate of Stage-III cancer patients (P < 0.05)." (PMID 33330092, 2020). "The patients with BTG1-positive cancer showed lower serum level of CEA and CA19-9 than those with BTG1-negative cancer (P < 0.05)." (PMID 33330092, 2020). "BTG1 and BTG2 have been found to be frequently downregulated or mutated in several types of cancers, and the decreased expression of BTG1 and BTG2 is positively associated with malignant cell behavior and poor outcome in cancer patients." (PMID 32093041, 2020). "In contrast, BTG1 overexpression increased CEA expression and secretion, which was closely linked to a strong ability of cancer cells to migrate and invade." (PMID 33330092, 2020).
cancer (continued). "Evidences have shown that over expression of BTG1 can suppress cancer cell proliferation as well as migration and invasion." (PMID 30787206, 2019). "Here, we focus on the positive cell cycle regulator PUM2 and its potential target BTG1 which inhibits cancer cell proliferation and promotes apoptosis." (PMID 30787206, 2019). "In contrast, genes in neural (CDS1 and CHD4) and cancer-related (BTG1, COL6A1, PMP22 and HIF1A) pathways were increased by STAT3-KD, and their expression was reduced by STAT3 expression." (PMID 29774125, 2018). "In line with previous reports, we observed that BTG1 expression was lower in cancer than matched mucosa at the mRNA level, but higher at the protein level." (PMID 27447746, 2017). "There was a higher expression of BTG1 mRNA in normal tissue than in cancer tissue, and in benign tumors than in cancer tissue of the ovary." (PMID 26050197, 2015). "BTG1 was more expressed in elder male cancer patients than that in their younger female counterparts (p < 0.05)." (PMID 26050197, 2015). "RCC tissues and cells exhibited significantly weaker BTG1 protein and mRNA expression compared with para-carcinoma control tissues (P<0.05)." (PMID 26622543, 2015). "The diffuse-type carcinomas showed less BTG1 expression than intestinal- and mixed-type ones (p < 0.05)." (PMID 26050197, 2015). "BTG1 mRNA expression was lower in carcinomas and higher in normal ovarian tissue, indicating that downregulated BTG1 expression contributes to ovarian epithelial carcinogenesis." (PMID 24084718, 2013). "We examined BTG1 mRNA expression in ovarian normal tissue, benign tumors, and carcinomas and compared it with clinicopathological parameters to clarify the roles of BTG1 in ovarian carcinogenesis and subsequent progression." (PMID 24084718, 2013). "There was higher expression of BTG1 mRNA in normal tissue than in carcinoma tissue (p = 0.001) and in benign tumors than in carcinoma tissue (p = 0.027)." (PMID 24084718, 2013). "BTG1 belongs to the BTG/TOB family of anti-proliferative genes (BTG1-BTG4, TOB1 and TOB2) implicated in several types of cancer." (PMID 22359517, 2012). "The B-cell translocation gene 1 (BTG1) could reverse the miR-22 for the inhibition of autophagy, while the miR-4295 could significantly promote the proliferation and migration of cancer cells via directing the BTG1." (PMID 40918450, 2025). "In addition to the regulation of apoptosis, the protein products of these genes are involved in signaling pathways that are associated with cancer development and progression, including NF-ĸB (BCL3, SPHK1, and PRKCZ) and c-MYC (PIM1 and BTG1)." (PMID 38731835, 2024). "Negative association between BTG1 expression and overall prognosis was observed in the cancer patients only receiving surgical operation (p < 0.05)." (PMID 36339000, 2022). "Taken together, BTG1 should be used as a molecular target for cancer gene therapy." (PMID 36339000, 2022). "Taken together, BTG1’s high expression might be involved in the poor progression of several cancers, and might be considered as a marker indicating that BTG1 promotes migration, invasion, and/or metastasis." (PMID 36230852, 2022). "For example, studies have shown that antiproliferative BTG1 acts synergistically with paclitaxel in certain cancer cell lines: cells with induced BTG1 overexpression were more sensitive to paclitaxel and exhibited lower post-treatment expression of chemoresistance genes than controls." (PMID 33654134, 2021). "The distinct expression apoptosis-related genes and their encoding proteins might underlie molecular mechanism of the difference in apoptotic alteration of both BTG1-overexpressing cancer cells." (PMID 27447746, 2017). "Btg1 and Btg2 proteins regulate various cellular processes including proliferation, differentiation and apoptosis, while deregulated expression has been observed in various cancers, including B cell malignancies." (PMID 26218146, 2015).
cancer (continued). "There was higher expression of BTG1 mRNA in normal tissue than in carcinoma tissue (p = 0.001) and in benign tumors than in carcinomas (p = 0.027), as well as in International Federation of Gynecology and Obstetrics (FIGO) stage I/II carcinomas than in FIGO stage III/IV carcinomas (p = 0.038)." (PMID 24084718, 2013). "However, regulation of BTG1 in cancers of CNS remains unexplored." (PMID 30787206, 2019). "The APRO family includes 6 members: Tob1, Tob2, BTG1, BTG2, Abundant in Neuroepithelium Area (ANA), and BTG4, which some members are of significance for the prognosis of cancers." (PMID 40918450, 2025). "PRMT1 binds to ATF4 in a BTG1-dependent manner, and PRMT1 methylates ATF4, promoting transcription of some target genes of ATF4, leading to increased apoptosis in cancer cells." (PMID 38326807, 2024). "We used bioinformatics methods to analyze the characteristics of TOB1, TOB2, BTG1, BTG2, BTG3 and BTG4 in pan-cancer." (PMID 38062199, 2023). "Through a series of bioinformatics analysis, the findings in our study supported the important role of TOB1, TOB2, BTG1, BTG2, BTG3 and BTG4 in pan-cancer and provided a reliable basis for detecting biomarkers of cancer." (PMID 38062199, 2023). "BTG1 belongs to the BTG/Tob families, had been proved to inhibit various cancer cells growth, and expresses primarily in the G0/G1 phase transition, with levels decreasing as cells enter S phase." (PMID 37056757, 2023). "In the present study, we comprehensively analyzed the role of TOB1, TOB2, BTG1, BTG2, BTG3 and BTG4 in cancer from the perspective of bioinformatics." (PMID 38062199, 2023). "Real-time RT-PCR and western blotting revealed that BTG1 mRNA and protein expression, respectively, were higher in CAOV3 cells as compared with other carcinoma cells (p < 0.05)." (PMID 24084718, 2013). "Both BTG1 and BTG2 are closely correlated with the prognosis of cancer patients." (PMID 40918450, 2025). "Additionally, PRMT1 binds to ATF4 in a BTG1-dependent manner, methylating ATF4 and promoting the transcription of certain target genes of ATF4, leading to increased apoptosis of cancer cells." (PMID 38326807, 2024). "The correlation between BTG1 expression and prognosis of the cancer patients did not parallel with the alteration in BTG1 expression in cancer tissues." (PMID 36339000, 2022). "Negative correlation between overall survival and BTG1 expression was found in the patients with stage II and IV, T2, N3, intestinal and mixed or Her2-positive cancers (p < 0.05)." (PMID 36339000, 2022). "The overall survival rate of the patient with ER (estrogen receptor)-negative, grade-3, or luminal-B cancer was higher in the group of high BTG1 expression than that in its low expression (p < 0.05, data not shown)." (PMID 36339000, 2022). "There appeared a negative relationship between BTG1 expression and the overall survival rate of the cancer patients with paclitaxel treatment (p < 0.05)." (PMID 36339000, 2022). "There appeared to be a positive relationship between BTG1 expression and the progression-free survival rate of cancer patients without chemotherapy or margin invasion (p < 0.05, data not shown)." (PMID 36339000, 2022). "Using the Oncomine, TCGA (the cancer genome atlas), xiantao, UALCAN (The University of ALabama at Birmingham Cancer data analysis Portal), and Kaplan-Meier plotter databases, we undertook a bioinformatics study of BTG1 mRNA expression in cancers." (PMID 36339000, 2022). "Patients with Her2-negative and luminal-B cancer who had high BTG1 expression had a longer time without distant metastasis than those who had low BTG1 expression (p < 0.05, data not shown)." (PMID 36339000, 2022). "Kaplan–Meier analysis showed the negative correlation between BTG1 mRNA expression and overall survival rate of all cancer patients (P < 0.05)." (PMID 33330092, 2020).